CHAF1A (chromatin assembly factor 1 subunit A)
Diseases named in the same sentence as CHAF1A in open-access papers (continued):
Sharing a sentence is not in itself a finding about the gene and the disease.
lymphoma (2 papers, 2021 to 2022). A malignant (clonal) proliferation of B- lymphocytes or T- lymphocytes which involves the lymph nodes, bone marrow and/or extranodal sites. "However, no studies are currently reported to elucidate the underlying associations between CHAF1A and lymphoma, especially the DLBCL." (PMID 35773729, 2022). "Furthermore, dysregulation of CHAF1A correlates tightly with genomic instability and leads to high morbid risks of leukemia, lymphoma, or other solid tumors." (PMID 35773729, 2022).
acute myeloid leukemia (1 paper, 2024). Acute myeloid leukemia (AML) is a group of neoplasms arising from precursor cells committed to the myeloid cell-line differentiation. "Supporting these findings are reports showing that CEBPA knockdown decreases Chaf1a expression, and that patients with acute myeloid leukemia that have CEBPA double mutations have decreased Chaf1a levels." (PMID 38392328, 2024).
astrocytoma (1 paper, 2016). "Moreover, a decreased risk of astrocytoma subtype associated with the C alleles of CHAF1A rs243341 and rs2992 as well as the T allele of XRCC1 rs25487 involved in DNA repair pathway was detected (pDOM=0.040, pDOM=0.049, and pDOM=0.033, respectively)." (PMID 27613841, 2016). "Moreover, the C alleles of CHAF1A rs243341 and rs2992 as well as the T allele of XRCC1 rs25487 were associated with a decreased risk of astrocytoma subtype." (PMID 27613841, 2016). "Furthermore, polymorphisms in CHAF1A and XRCC1 are associated with the risk of astrocytoma, whereas SNPs in EME1, ATM, GLTSCR1, and XRCC4 are associated with susceptibility to non-astrocytoma subtypes." (PMID 27613841, 2016). "In the astrocytoma subgroup, the CHAF1A block (rs243341, rs105038, rs243356, and rs2992) with three haplotypes with frequency of >1% was found; however, the distribution of haplotypes in this haploblock was not significantly different between patients and controls (χ2 = 2.95, df = 2, p = 0.229)." (PMID 27613841, 2016).
breast invasive carcinoma (1 paper, 2023). "In cBioPortal database, the list of co-expression genes of CHAF1A in breast invasive carcinoma were downloaded, including three cohorts of TCGA data: Nature 2021, Cell 2015, and Firehose Legacy." (PMID 36968583, 2023).
Burkitt lymphoma (1 paper, 2022). A rare form of malignant mature B-cell non-Hodgkin lymphoma. "Similarly, STAT3 and CEBPB in SNB19 cell line, CHAF1A in IMR32 cell line, and BCL6 in Burkitt lymphoma cell line were identified by RegEnrich, with the GSEA method, as one of the top 20 key regulators in each corresponding dataset." (PMID 35017649, 2022).
cervical cancer (1 paper, 2021). A primary or metastatic malignant neoplasm involving the cervix. "CHAF1A protein overexpression in cervical cancer is a poor prognostic factor that is associated with advanced stage, increased percentage of local recurrence, metastasis, and lower OS." (PMID 34073937, 2021). "In cervical cancer cell lines, CHAF1A was shown to regulate cell proliferation, migration, and invasion, driving the essential biological processes for tumorigenesis and metastasis." (PMID 34073937, 2021).
diffuse large B-cell lymphoma (1 paper, 2022). "This study planed to uncover the biological roles of epigenetic SPOP/CHAF1A axis in modulating tumor autophagy during Diffuse large B-cell lymphoma (DLBCL) tumorigenesis." (PMID 35773729, 2022).
esophageal cancer (1 paper, 2023). A primary or metastatic malignant neoplasm involving the esophagus. "Here, we combine them and propose that the co-expression of CHAF1A and PCNA is a prognostic biomarker for esophageal cancer." (PMID 37189802, 2023). "Western blotting of 17 esophageal cancer cell lines showed that the expression of CHAF1A and PCNA were not completely consistent." (PMID 37189802, 2023).
lentivirus infection (1 paper, 2022). Virus diseases caused by the Lentivirus genus. "Conversely, SPOP overexpression by lentivirus infection significantly shortened the half-life of CHAF1A protein." (PMID 35773729, 2022). "To validate whether CHAF1A exerts a biological impact in DLBCL, we performed the gain- and loss-of-function assays using lentivirus infection technology." (PMID 35773729, 2022).
macrosomia (1 paper, 2025). "Western blot analysis of placental tissue also indicated that the expression of CHAF1A was increased in the GDM with macrosomia group (P < 0.05)." (PMID 40797060, 2025). "CHAF1A expression was compared between the GDM with macrosomia group (n = 25) and the normal glucose with normal weight group (n = 15), and the correlation between CHAF1A and neonatal body composition was examined." (PMID 40797060, 2025). "Immunohistochemistry revealed significantly higher expression of CHAF1A in the GDM with macrosomia group (P < 0.05)." (PMID 40797060, 2025). "Placental immunohistochemistry showed that the expression of CHAF1A in the GDM with macrosomia group was significantly higher than that in the control group (P < 0.05)." (PMID 40797060, 2025). "This study aims to investigate the role and underlying mechanisms of Chromatin assembly factor 1 subunit A (CHAF1A) in GDM-induced macrosomia." (PMID 40797060, 2025). "We discovered that CHAF1A was highly expressed in the placentas of GDM induced macrosomia and that CHAF1A was positively correlated with neonatal body composition parameters." (PMID 40797060, 2025). "This study aimed to investigate the role of CHAF1A in GDM-induced macrosomia., and to investigate the effects of CHAF1A on the proliferation and differentiation of preadipocytes as well as its underlying mechanisms." (PMID 40797060, 2025). "In conclusion, we found that CHAF1A expression was higher in placentas of GDM women with macrosomia, and positively correlated with neonatal body composition." (PMID 40797060, 2025). "Our study investigated the role of CHAF1A in GDM-induced macrosomia and its regulation of adipogenesis-related factors, revealing that CHAF1A is a key player in adipogenesis and providing new insights into the pathogenesis of GDM-associated macrosomia." (PMID 40797060, 2025). "CHAF1A promotes the proliferation and differentiation of preadipocytes, which may be a direction for exploring fetal fat accumulation leading to macrosomia in GDM." (PMID 40797060, 2025). "In the future, direct evidence from fetal adipose tissue and transplacental studies will be needed to clarify the specific pathways and mechanisms by which CHAF1A influences fetal fat production, thereby providing new insights into the pathogenesis of GDM-related macrosomia." (PMID 40797060, 2025). "Moreover, CHAF1A overexpression was positively correlated with neonatal birth weight, F%, FM, and SFT4, suggesting that CHAF1A may play a key role in fat accumulation and weight gain in GDM-induced macrosomia." (PMID 40797060, 2025).
non-small cell lung carcinoma (1 paper, 2021). A group of at least three distinct histological types of lung cancer, including non-small cell squamous cell carcinoma, adenocarcinoma, and large cell carcinoma. "CHAF1A mRNA and protein levels are higher in non-small cell lung carcinoma (NSCLC) tissues in comparison with normal lung parenchyma." (PMID 34073937, 2021).
Obesity (1 paper, 2024). Accumulation of substantial excess body fat. "Several potential functional genes, including CHAF1A, CEP192, ULK4, CYP2D6, AS3MT, and WARS2, were identified as common genetic factors linking obesity and IS." (PMID 39734234, 2024). "The identification of CHAF1A, CEP192, ULK4, CYP2D6, AS3MT, and WARS2 as potential functional genes common to both obesity and IS enriched our understanding of their genetic interplay, potentially advanced our grasp of their pathogenesis and therapeutic targets." (PMID 39734234, 2024).
ovarian tumors (1 paper, 2022). "We thus investigated if CHAF1A levels impact the chemosensitivity of BRCA-mutant ovarian tumors in clinical samples." (PMID 36085347, 2022).
rectal cancer (1 paper, 2019). A primary or metastatic malignant neoplasm that affects the rectum. "In addition to SMAD7 (P = 0.0005) and SMAD3 (P = 0.0003), several other genes or genetic regions (CYP2R1, CHAF1A, CREBBP, IL10, SNPs identified in genome-wide association studies (GWAS) to be associated with IGF levels, IGFBP2/IGFBP5, IGFBP3, and C-MYC region) were associated with rectal cancer." (PMID 31434255, 2019).
tumor (20 papers, 2012 to 2025). "Tumor immunosuppressive microenvironment was also explored to find out the association between CHAF1A and immune cells." (PMID 36968583, 2023). "Deficient SPOP contributes to accumulated CHAF1A proteins, thereby sustaining tumor autophagy via induction of TFEB." (PMID 35773729, 2022). "Down-regulated or DLBCL-associated SPOP mutations contribute to CHAF1A accumulations, thereby enhancing tumor autophagy of DLBCL in a TFEB-dependent manner." (PMID 35773729, 2022). "Overexpression of the CHAF1A protein is associated with advanced tumour stage, high-grade (poor differentiation) histology, and tumour invasion, and is an independent prognostic factor of poor clinical outcome (reduced OS and DFS)." (PMID 34073937, 2021). "Overexpression of the CHAF1A protein is associated with tumour recurrence, metastatic spread, and poor outcomes (shorter OS and disease-free survival (DFS) rates)." (PMID 34073937, 2021). "SPOP deficiency mainly depended on CHAF1A to accelerate in vivo DLBCL tumor growth." (PMID 35773729, 2022). "CHAF1A expression also predicted microsatellite instability (MSI) and a high tumor mutation burden (TMB)." (PMID 38254099, 2024). "The CHAF1A IHC scores positively correlated with the density of NK cells (Pearson R = 0.74, p = 0.037) in the tumor parenchyma and macrophages M1 in the stroma (R = 0.75, p = 0.031)." (PMID 38254099, 2024). "Among the 22 paired tumor and corresponding normal samples, the expression of CHAF1A was significantly elevated in 20 types of malignancies compared with normal tissues." (PMID 36968583, 2023). "In view of the high correlation between CHAF1A and PCNA protein expression in EC tumor tissues, we next analyzed the effect of CHAF1A and PCNA protein co-expression on patient prognosis." (PMID 37189802, 2023). "In vivo studies revealed the pro-tumorigenic effect of CHAF1A/B, showcasing that its overexpression promoted tumor growth." (PMID 36428674, 2022). "Given that SPOP/CHAF1A axis modulates the DLBCL tumor autophagy, we further detected the level of autophagy in DLBCL cells." (PMID 35773729, 2022). "Given that little was reported about the roles of TFEB in DLBCL, we found that CHAF1A mainly depends on activated TFEB to drive tumor progression." (PMID 35773729, 2022). "Taken together, SPOP/CHAF1A axis restricts tumor autophagy in a TFEB-dependent manner, and targeting TFEB-mediated signaling represents a useful strategy for SPOP-deficient DLBCL." (PMID 35773729, 2022). "In vitro data suggest that high expression of CHAF1A induces tumour cell proliferation and inhibits apoptosis via the Akt-mediated activation of the Foxo3a/Bim signalling pathway." (PMID 34073937, 2021). "CHAF1A protein overexpression in glioblastoma correlates with increased tumour size, advanced grade (III or IV according to WHO classification), and poor OS." (PMID 34073937, 2021). "The overexpression of CHAF1A protein in neuroblastoma contributes to increased proliferation and tumour growth, and is an independent prognostic factor for advanced stage, and reduced DFS and OS." (PMID 34073937, 2021). "Mice were fed with control chow (CHAF1A OFF) or doxycycline (DOX)‐containing chow to induce CHAF1A expression (CHAF1A ON), and tumor formation was assessed 5 weeks after xenograft implantation (left)." (PMID 34365742, 2021). "BKM120-induced reduction in the levels of CHAF1A and Caspase 3, pATR, DRIP130, EZH2, and Ki67 was associated with more effective tumor growth inhibition, while increased phosphorylation of Aurora kinases was associated with resistance." (PMID 33371187, 2020). "Thereby, the elevated expression of CHAF1A might be related with suppressive tumor microenvironment resulting in poor survival outcome." (PMID 36968583, 2023). "Notably, in line with in vitro results, mice with overexpressing CHAF1A suffered from more serious tumor burden and higher Ki-67 staining levels relative to those in the control group." (PMID 35773729, 2022).
tumor (continued). "Given that TFEB is the master transcription factor in the regulation of lysosomal biogenesis and autophagy, we thus wondered whether CHAF1A could modulate tumor autophagy process via TFEB activation." (PMID 35773729, 2022). "Therefore, our study provided a novel link between SPOP/CHAF1A axis and tumor autophagy of DLBCL, acting as the basis for finding novel epigenetic targets for DLBCL treatment." (PMID 35773729, 2022). "The subcutaneous mice model further suggested that CHAF1A could promote in vivo tumor growth, as revealed by larger tumor volumes and tumor weight." (PMID 35773729, 2022). "To further determine whether DFMO+RA phenocopies genetic depletion of CHAF1A+RA in terms of tumor growth inhibition, we implanted LAN5 luc shCTRL and shCHAF1A cells into the renal capsule of 7‐week‐old female NCr nude mice." (PMID 34365742, 2021). "Additionally, CHAF1A expression correlated with increased tumour size, simultaneous multiple tumours, advanced stage, and higher Edmondson–Steiner histologic grade." (PMID 34073937, 2021). "Inhibiting the CHAF1A-TFEB signaling pathway may further suppress tumor growth and survival." (PMID 40521202, 2025). "However, targeting CHAF1A could abrogate the facilitative effect of SPOP loss on tumor growth, as indicated by tumor volumes and weight." (PMID 35773729, 2022). "Zheng and Xu unearthed that CHAF1A expression is elevated in patients with HCC and GC and correlates with tumor cell proliferation." (PMID 36428674, 2022). "In conclusion, we obtained several DEGs in CC and found that overexpression of DNMT1, CHAF1B, CHAF1A, MCM2, KNTC1 in tumor tissues predicted poor survival in CC." (PMID 33616161, 2021). "In contrast with CHAF1B, CHAF1A protein expression inversely correlates with PCNA levels and is downregulated in aggressive tumours." (PMID 34073937, 2021). "CHAF1A and RMI1 expression are remarkably higher in tumor tissues of GC when compared with normal samples (all P < 0.0001)." (PMID 33785812, 2021). "Again, the dysregulation of CEP55, CLDN4, CHAF1A, H19 and STEAP4 have been found to significantly correlate with CRC tumor stage, aggressiveness, metastasis and poor prognosis." (PMID 30823889, 2019). "Notably, CHAF1A and PCNA expression were significantly upregulated in the EC tissues compared to non-tumor tissues." (PMID 37189802, 2023). "Given that previous studies showed that SPOP could restrict tumor autophagy via p62, we thus questioned whether SPOP could depend on CHAF1A/TFEB to regulate autophagy." (PMID 35773729, 2022). "CHAF1A expression is upregulated in luminal B and basal-like tumours in comparison to luminal A tumours, but does not differ between luminal A and HER2-positive tumours." (PMID 34073937, 2021). "To further determine the contribution of CHAF1A to NB oncogenesis, we orthotopically implanted SHEP cells with and without conditional CHAF1A overexpression into the renal capsule of nude mice and then assessed tumor growth." (PMID 34365742, 2021).
cancer (14 papers, 2013 to 2025). A tumor composed of atypical neoplastic, often pleomorphic cells that invade other tissues. "The analysis of co-expression gene network demonstrated CHAF1A was associated with not only cell proliferation, DNA repair, apoptosis, but cancer metabolism, immune system, and drug resistance." (PMID 36968583, 2023). "In general, the current study demonstrated that elevated expression of CHAF1A can be used as diagnostic biomarker in various types of human cancers." (PMID 36968583, 2023). "Recently, CHAF1A has been revealed to be upregulated and associated with cell differentiation, proliferation, and apoptosis resistance in multiple cancers, including GC30,31." (PMID 33785812, 2021). "Increasing reports have found that CHAF1A was closely associated with cell cycle regulation and showed a pivotal relationship with the formation and prognosis of various cancers, which can served as a biomarker to distinguish quiescent from proliferating cells." (PMID 33785812, 2021). "Taken together, these findings improve our understanding of the mechanisms that regulate the TLS pathway and provide insights into the relationship between CHAF1A and DNA replication stress in cancer cells." (PMID 40025006, 2025). "Here, we demonstrate a novel function of CHAF1A in regulating PCNA K164 monoubiquitination mediated-TLS pathway in cancer cells." (PMID 40025006, 2025). "Taken together, the data indicated that no major alterations in either sequence or copy number of the CHAF1A gene were responsible for cancer development." (PMID 36968583, 2023). "In consistent with the result from TIMER 2.0 database, it was also found abnormally high expression of CHAF1A in 36 study cohorts covering 17 types of cancers in Oncomine database." (PMID 36968583, 2023). "In order to identify the contribution of CHAF1A gene in human cancers, COSMIC (v94 GRCh38) was applied for genomic alteration assessment." (PMID 36968583, 2023). "In our study, we took a comprehensive approach to investigate the genomic alterations of CHAF1A and demonstrate CHAF1A expression profiles in various cancer types." (PMID 36968583, 2023). "In the latest released version of COSMIC, CHAF1A was tested in 39,615 cancer samples across 40 different types of cancer." (PMID 36968583, 2023). "Some of these functions and mechanisms of CHAF1A were reported in other cancer types, however, most of these were shown in the first time." (PMID 36968583, 2023). "The expression of CHAF1A was significantly up-regulated in most tumors in pan-carcinoma unpaired samples by bioinformatics analysis, and significantly up-regulated in most tumors in pan-carcinoma paired samples." (PMID 37575547, 2023). "CHAF1A knock-down experiments in the H1299 NSCLC cell line indicate that CHAF1A promotes proliferation and inhibits apoptosis in cancer cells, effects that are blocked by the overexpression of miR-520b, which directly targets CHAF1A." (PMID 34073937, 2021). "Therefore, we believe that RAD18 recruitment to the stalled replication fork is performed by a number of proteins, including CHAF1A, to enable cancer cells to rapidly respond to DNA replication stress." (PMID 40025006, 2025). "Here, we revealed that CHAF1A is a novel regulator of the TLS pathway in cancer cells." (PMID 40025006, 2025). "Moreover, in order to verify the effect of CHAF1A on the survival ability of cancer cells under DNA replication stress, we treated KYSE510 and A549 cells with different doses of UV and measured cell survival with a colony formation assay." (PMID 40025006, 2025). "Recently, regulators similar to CHAF1A in chromatin organization and remodeling have been reported to play critical roles in anticancer immunity, and have therefore become promising targets for cancer treatment." (PMID 38254099, 2024). "CHAF1A has been reported to act as an oncogenic factor in many cancers." (PMID 37189802, 2023). "Genetic alterations affecting CHAF1A in 39,615 cancer samples (COSMIC database)." (PMID 36968583, 2023).